LINC02449 (long independently transcribed non-coding RNA 2449)
Gene: Long non-coding RNA gene on chromosome 12 (8,227,280 to 8,370,233, forward strand). Ensembl gene ENSG00000215241.
Diseases named in the same sentence as LINC02449 in open-access papers:
LINC02449 is named in the same sentence as 1 disease in open-access papers, as found by Europe PMC text mining. Sharing a sentence is not in itself a finding about the gene and the disease.
LINC02449 shares sentences with these, for which no sentence is quoted: psychiatric disorder (1 paper).